LINC00261 (long independently transcribed non-coding RNA 261)
Synonyms: bA216C10.1; HCCDR1; TCONS_00027846; ALIEN; DEANR1; onco-lncRNA-17; FALCOR; LCAL62; C20orf56; NCRNA00261
Gene: Long non-coding RNA gene on chromosome 20 (22,547,663 to 22,578,642, reverse strand). Ensembl gene ENSG00000259974.
Pathways (Reactome):
Developmental Biology: Formation of definitive endoderm
Diseases named in the same sentence as LINC00261 in open-access papers:
LINC00261 is named in the same sentence as 38 diseases in open-access papers, as found by Europe PMC text mining. Sharing a sentence is not in itself a finding about the gene and the disease. The quoted sentences say what the papers report.
pancreatic cancer (19 papers, 2019 to 2025). "KLF13 was confirmed to inhibit the EMT process of pancreatic cancer by promoting the transcription of LINC00261 and suppressing the expression of metastasis-associated proteins, thus, inhibiting the metastasis of pancreatic cancer." (PMID 37239940, 2023). "Here, we identified a previously uncharacterized polypeptide, N1DARP, encoded by LINC00261, through RNA sequencing and ribosome profiling, as a novel tumor suppressor and chemotherapy sensitizer for use in pancreatic cancer therapy, which acts by interfering with USP10–N1ICD interaction." (PMID 37714834, 2023). "As a well-studied lncRNA, C20orf56 (LINC00261) has been widely studied in pancreatic cancer, prostate cancer, non-small cell lung cancer, bile duct cancer, colon cancer, endometrial cancer and other tumors." (PMID 37859697, 2023). "For human functional analog DEANR1/linc00261, there are published data concerning the involvement of lncRNA in the regulation of glycolysis in pancreatic cancer." (PMID 35740417, 2022). "Dysregulation of LINC00261 has been found to play vital roles in pancreatic cancer, gastric cancer, hepatocellular carcinoma, and colon cancer." (PMID 36330513, 2022). "Recently it was demonstrated that the LL35 functional analog in humans, linc00261, participates in the regulation of pancreatic cancer glycolysis and proliferation and also induces cell cycle arrest and apoptosis." (PMID 35740417, 2022). "LINC00261 was confirmed by other studies to act as a tumor suppressor gene in prostate cancer, breast cancer, pancreatic cancer and many other types of cancers." (PMID 33928038, 2021). "In this study, using bioinformatic analysis followed by biological validation, we revealed epigenetic modification resulting in aberrant expression of LINC00261 in pancreatic cancer." (PMID 33122827, 2021). "LINC01111/miR-3924, LINC01963/miR-641, DGCR5/miR-27a-3p, GAS5/miR-32-5p, and LINC00261/miR-23a-3p axes are examples of the latter type of lncRNA/miRNA interactions in the context of pancreatic cancer." (PMID 34827663, 2021). "Apart from downstream pathways through which LINC00261 exerts its tumor suppressive functions, we also investigated the reason for its downregulation in pancreatic cancer, which has rarely been reported." (PMID 33122827, 2021). "LINC00261 acts as a tumor suppressor gene in many cancers, LINC00261 suppresses the growth and metastasis of liver cancer, prostate cancer, and pancreatic cancer." (PMID 34336838, 2021). "Furthermore, miR-23a-3p is a recognized target of LINC00261; its overexpression can curtail the growth and metastasis of pancreatic cancer cells while promoting apoptotic pathways through the reduction of miR-23a-3p levels." (PMID 40462237, 2025). "It has been discovered that LINC00261 has unique epigenetic and post-transcriptional regulation mechanisms that act as tumor suppressors in pancreatic cancer, which could be beneficial for pancreatic cancer targeted treatment." (PMID 39346921, 2024). "LINC00261 can also be over-expressed in pancreatic cancer tissues by binding miR-222-3p to activate the HIPK2/ERK/c-myc pathway 43, which unmasked a new epigenetic and post-transcriptional regulatory mechanism that contributes to targeted therapy for pancreatic cancer." (PMID 37859697, 2023). "Also, Linc00261 has been recognized as a novel prognostic marker in many carcinomas, such as gastric cancer, pancreatic cancer, and hepatocellular carcinoma." (PMID 35465017, 2022). "Our study suggests that LINC00261 functions as a tumor suppressor in pancreatic cancer and identifies novel epigenetic and posttranscriptional regulatory mechanisms of LINC00261, which contribute to the targeted therapy of pancreatic cancer." (PMID 33122827, 2021). "To investigate the mechanism mediating the downregulation of LINC00261 in pancreatic cancer, we hypothesized that DNA methylation could be involved." (PMID 33122827, 2021).
pancreatic cancer (continued). "LINC00261 expression plays an important role in cell proliferation, apoptosis and invasion in choriocarcinoma and gastric cancer, and was identified as a novel prognostic biomarker in pancreatic cancer." (PMID 32860342, 2020). "To gain further insights into the potential mechanism of LINC00261-mediated downregulation of E-cadherin, we performed nuclear and cytoplasmic fractionation experiments in lung and pancreatic cancer cell lines to obtain information about the subcellular localization of LINC00261." (PMID 32414223, 2020). "Although several studies have demonstrated that LINC00261 could function as a tumor suppressor in pancreatic cancer through its role in cell proliferation, migration, and invasion, which is partially in accordance with our results, whether LINC00261 regulates glycolysis remains unclear." (PMID 33122827, 2021). "In addition, methylation-specific PCR (MSP) analysis further validated these results, showing that pancreatic cancer tissues had high methylation levels compared with normal tissue, and the expression of LINC00261 was inversely correlated with the methylation levels in the promoter region." (PMID 33122827, 2021). "We also identified that the low expression of MEG3, LINC01963, and LINC00261 and the high expression of MACC1-AS1, LINC00462, LINC01559, and UCA1 were significantly correlated with worse survival in pancreatic cancer patients." (PMID 34827663, 2021). "Thus, the sequence of events during pancreatic cancer tumorigenesis is upregulation of KLF13, resulting in increased levels of LINC00261 and a decrease in PI3K/AKT/mTOR pathway activity, leading to a decline in metastasis." (PMID 37239940, 2023). "The downregulation of LINC00261, as it occurs in the progression of PDAC, may contribute to the EMT of pancreatic cancer cells, at least partly due to its direct effect on E-cadherin." (PMID 32414223, 2020). "Taken together, these results indicate that LINC00261 might be involved in the regulation of CDH1 transcription, thereby controlling the epithelial identity of pancreatic cancer cells." (PMID 32414223, 2020). "In addition, we confirmed the reduced expression of LINC00261 and MEG3, which are thought to function as tumour-suppressive lincRNAs in pancreatic cancer, and especially in neuroendocrine neoplasms in the case of MEG3." (PMID 32727085, 2020). "Hence, based on their abundance, significant downregulation and their prognostic relevance, LINC00261 and NEAT1 might be interesting candidates for functional follow-up studies to dissect their cellular and molecular functions in pancreatic cancer." (PMID 32727085, 2020).
gastric cancer (15 papers, 2014 to 2022). A primary or metastatic malignant neoplasm involving the stomach. "LINC00261 downregulation in gastric cancer is associated with poor prognosis." (PMID 36386809, 2022). "At the same time, miR-1269a can interact with RP11-1094M14.8, LINC00261, and circASS1 in gastric cancer, lung cancer, and colon cancer, respectively." (PMID 35252180, 2022). "Linc00261, also known as DEANR1, has been found dysregulated in numerous cancers, such as lung cancer, gastric cancer, endometrial cancer, and HCC." (PMID 35123494, 2022). "The function of linc00261 has been investigated in multiple cancers, it suppressed lung and gastric cancer progression and metastasis by attenuated EMT, and function as a tumor suppressor in varies of human cancers by sponging with miRNA or affecting pathways." (PMID 35123494, 2022). "For example, LINC00261, which plays an important role in gastric cancer, is stimulated by GnRHa, and exerts tumor suppressive activity by reducing cancer cell invasion via suppression of the epithelial-mesenchymal transition process." (PMID 31890219, 2019). "A study showed that patients with low expression levels of LINC00261 had a higher recurrence rate than those with high expression levels of LINC00261 in gastric cancer, suggesting that patients with low expression levels of LINC00261 have a poor prognosis." (PMID 31179185, 2019). "Lower expression of LINC00261 correlates with deeper tumor invasion, poorer differentiation and lymph node metastasis in stomach cancer." (PMID 28484081, 2017). "Also, downregulation of LINC00261 is also correlated with the poor prognosis and inhibits cancer metastasis in gastric cancer." (PMID 34446696, 2021). "For example, LINC00261 expression is reduced in gastric cancer cells and LINC00261 suppressed cell invasion of gastric cancer, indicating that LINC00261 could be a new biomarker for gastric cancer." (PMID 33013201, 2020). "Importantly, upregulation of LINC00261 could suppress cell proliferation and metastasis in several human cancers such as choriocarcinoma, gastric cancer, and HCC." (PMID 34446696, 2021). "It has been reported that Linc00261 suppresses epithelial-mesenchymal transition (EMT) progression in several cancers, such as gastric cancer and non-small cell lung cancer." (PMID 35465017, 2022). "The deletion of LINC00261 has been observed in a variety of malignant tumors including HCC, breast cancer, and gastric cancer." (PMID 34324544, 2021). "In a previous study it was shown that LINC00261 could bind to SNAI2 and promote its degradation in gastric cancer." (PMID 32414223, 2020). "Whether LINC00261 plays any functional role in lung cancer progression or EMT is an unanswered question, but its overexpression in gastric cancer suppressed metastasis by direct interaction and degradation of the EMT-associated transcription factor Slug." (PMID 30597925, 2018).
colon cancer (13 papers, 2014 to 2025). "Mechanistically, LINC00261 repressed colon cancer progression by inactivating the Wnt signaling pathway by modulating miR-324-3p." (PMID 40136629, 2025). "LINC00261 is a tumor suppressor in colon cancer, showing that its overexpression inhibits cell growth and migration, and deactivates the Wnt signaling pathway." (PMID 40136629, 2025). "For example, DNAJC3-AS1, EGOT, and LINC00261 are considered clinical markers of colon cancer and are involved in regulating cell proliferation and invasion." (PMID 37448887, 2023). "LINC00261 downregulation is observed in cisplatin-resistant colon cancer cells, while LINC00261 upregulation reverses cisplatin resistance and enhances the cisplatin effects of this drug via inactivation of the β-catenin/WNT pathway." (PMID 33246471, 2020). "Overexpression of LINC00261 also suppresses colon cancer metastasis by sequestering β-catenin in the cytoplasm, facilitating its degradation and suppressing Wnt signaling." (PMID 30597925, 2018). "From the data above, we can conclude that LINC00261 could be linked to CRC patients’ prognoses, indicating that it could be a useful biomarker for patients with colon cancer." (PMID 40136629, 2025). "Moreover, low LINC00261 expression also correlates with cisplatin resistance in colon cancer cell lines and overexpression sensitizes them to anticancer DNA-damaging agents." (PMID 30597925, 2018). "To conclude, our study revealed the role of LINC00261 in colon cancer cells drug resistance and might offer a new vision and direction for the treatment of colon cancer." (PMID 29267503, 2017). "LINC00261 overexpression might relieve cisplatin resistance of colon cancer cells via promoting cell apoptosis, and inhibiting cell viability, migration, and invasion." (PMID 29267503, 2017). "qRT–PCR experiments showed that CEBPA-DT, LINC00261 and LINC01315 expressions in colon cancer cells were significantly higher than those in NCM460 cells." (PMID 35911752, 2022). "LINC00261 overexpression has been demonstrated to promote cell apoptosis, whereas lncRNA ZFAS1 impedes colon cancer cell apoptosis." (PMID 33246471, 2020).
hepatocellular carcinoma (9 papers, 2019 to 2025). A malignant tumor that arises from hepatocytes. "LINC00261 is a tumor suppressor positively associated with prognosis in many tumors, such as hepatocellular carcinoma (Zhang, Li & Han, 2018a), endometrial carcinoma (Fang, Sang & Du, 2018) and non-small cell lung (Liu, Xiao & Xu, 2017)." (PMID 30755833, 2019). "Moreover, reduced expression of LINC00261 in hepatocellular carcinoma (HCC) tissues is associated with a reduced tumor-free survival time." (PMID 34446696, 2021). "LINC00261 is abnormally expressed in a variety of tumors such as gastric, colorectal, lung, breast, laryngeal, prostate, endometrial, esophageal, prostate, cholangiocarcinoma, and hepatocellular carcinoma." (PMID 40699747, 2025). "Additionally, LINC00261 interacts with specific miRNAs; for instance, it binds with miR-23a-3p and miR-552-5p in PC, miR-148a, and miR-324-3p in colorectal cancer, miR-522-3p and miR105-5p in hepatocellular carcinoma, to downregulate oncogenic pathways in these cancers." (PMID 40136629, 2025). "We checked the LL35 RNA level in murine HCC tissue and found its downregulation, similar to human linc00261; moreover, LL35 levels in several murine hepatocyte cell lines additionally proved the predominant expression of LL35 in normal liver cells compared to hepatoma cells." (PMID 35740417, 2022).
breast cancer (6 papers, 2014 to 2022). A primary or metastatic malignant neoplasm involving the breast. "LINC00261 expression has also been reported to reduce the proliferation and migration of breast cancer cells." (PMID 34022894, 2021). "Linc00261 expression is downregulated in several cancer types, such as HCC, pancreatic, gastric, colorectal, lung and breast cancers." (PMID 35740417, 2022). "Linc00261 expression is downregulated in HCC, pancreatic, gastric, colorectal, lung and breast cancers, playing a role of tumor suppressor." (PMID 35740417, 2022).
prostate carcinoma (6 papers, 2014 to 2023). A carcinoma that arises from epithelial cells of the prostate gland. "For example, LINC00261 is upregulated in prostate cancer, and LINC00261 knockdown suppresses cancer cell viability and invasiveness." (PMID 35075115, 2022). "Meanwhile, LINC00261 expression in human prostate cancer cell lines LNCap, PC-3, DU145, and 22Rv1, was declined compared to the normal prostate cell line RWPE-1, with the lowest expression found in LNCap." (PMID 33013201, 2020). "In our study, LINC00261 is expressed at a low level in prostate cancer, and LINC00261 negatively correlates with prostate cancer progression." (PMID 33013201, 2020). "Consist with the previous study, treatment with downregulation of DKK-3 facilitated malignant phenotypes of prostate cancer cells, upregulating MMP-2 and MMP-9, and even reversed the effect caused by overexpression of LINC00261." (PMID 33013201, 2020). "This suggested that LINC00261 inhibited the tumorigenesis of prostate cancer cells in vivo, and was a potential therapeutic target for prostate cancer." (PMID 33013201, 2020). "Thus, LNCaP was selected for subsequent experiments with the fact of lower expression of LINC00261 in prostate cancer." (PMID 33013201, 2020). "Overexpression of LINC00261 inhibited prostate cancer cells proliferation, migration, and invasion as well as angiogenesis, which could be reversed by silencing DKK3." (PMID 33013201, 2020). "Furthermore, upregulating LINC00261 expression suppressed the lumen formation of prostate cancer cells as well as inhibiting cell migration and invasion." (PMID 33013201, 2020). "In short, LINC00261 overexpression inhibited the proliferation, migration, invasion and tube formation of prostate cancer cells which could be reversed by DKK3 silencing." (PMID 33013201, 2020). "The GEPIA database further verified that LINC00261 is expressed at a low level in prostate cancer." (PMID 33013201, 2020). "However, the mechanism by which LINC00261 exerts its functions in prostate cancer is still unclear." (PMID 33013201, 2020). "LINC00261, GATA6, and DKK3 were poorly expressed in prostate cancer." (PMID 33013201, 2020). "Finally, we collected the prostate cancer data from the database and found that the expression of DKK3 was negatively correlated with the expression of LINC00261, and that patients with high expression of LINC00261 had a poor prognosis, which was consistent with our experimental results." (PMID 33013201, 2020). "Furthermore, the LINC00261/GATA6/DKK3 axis plays a crucial role in the development and prostate cancer progression; LINC00261-targeted GATA6 suppressed the proliferation, migration, invasion and angiogenesis of prostate cancer by promoting activation of DKK3." (PMID 33013201, 2020). "Furthermore, validation with GEPIA database revealed that DKK3 expression was also decreased in prostate cancer, which further demonstrated that LINC00261 might regulate DKK3 by binding to transcription factor GATA6, thus affecting the development of prostate cancer." (PMID 33013201, 2020).
lung carcinoma (5 papers, 2018 to 2022). "Hierarchical clustering of gene expression data from lung cancer cell lines could further verify the association of high LINC00261/FOXA2 expression to an epithelial gene signature." (PMID 30597925, 2018). "Hence, we explored whether LINC00261 could be associated with cell migration which is linked to lung cancer progression." (PMID 30597925, 2018). "The expression of LINC00261 is down-regulated in lung cancer, and the overexpression of LINC00261 inhibits the growth and metastasis of lung cancer by regulating the miR-1269a/FOXO1 axis." (PMID 35252180, 2022). "For example, LINC00261 was found to inhibit lung cancer cells by interfering with the expression of downstream miR-1269a." (PMID 33928038, 2021). "In lung cancer, LINC00261 is epigenetically regulated, with high methylation levels at the cg15058464 and cg07003030 loci, resulting in activation of the DNA damage response." (PMID 32929371, 2020). "Our data provides an important basis for future investigations on the role of the LINC00261/FOXA2 axis in lung cancer tumorigenesis, progression and metastasis to characterize their tumor suppressive and anti-metastatic functions in lung cancer." (PMID 30597925, 2018). "Interestingly, we observed that linc00261 was significantly down-regulated after treatment with TGF-β1, which is consistent with TGF-β1 induced-suppression of linc00261/Foxa2 in lung cancer cells." (PMID 35123494, 2022).
non-small cell lung carcinoma (5 papers, 2018 to 2023). A group of at least three distinct histological types of lung cancer, including non-small cell squamous cell carcinoma, adenocarcinoma, and large cell carcinoma. "Overexpression of LINC00261 inhibits cell proliferation and invasion and promotes apoptosis in non-small cell lung cancer cell lines." (PMID 36078096, 2022). "Interestingly, several genome-wide studies verified this cancer-specific expression profile of LINC00261 and a recent study also reported low LINC00261 expression as a prognostic marker for non-small cell lung cancer corroborating our results." (PMID 30597925, 2018).
choriocarcinoma (4 papers, 2020 to 2021). An aggressive malignant tumor arising from trophoblastic cells. "Overexpression of LINC00261 suppressed cell proliferation and invasion in human choriocarcinoma and inhibited migration of trophoblast in pre-eclampsia." (PMID 33013201, 2020). "In addition, LINC00261 overexpression was also shown to promote apoptosis and decrease cell proliferation in choriocarcinoma." (PMID 34022894, 2021). "As for Wnt signaling, LINC00261 participates it by promoting SFRP via ceRNA mechanism, and downregulated SFRP is proved to accelerate the tumorigenesis and metathesis of Choriocarcinoma." (PMID 34022894, 2021).